FOXP4 (forkhead box P4)
Diseases named in the same sentence as FOXP4 in open-access papers (continued):
Sharing a sentence is not in itself a finding about the gene and the disease.
medulloblastoma (4 papers, 2022 to 2025). A malignant, invasive embryonal neoplasm arising from the cerebellum. "For instance, miR-101-3p expression was significantly higher in plasma exosomes from medulloblastoma patients than in healthy groups, and played a vital role in tumorigenesis by targeting the FOXP4 gene." (PMID 40666104, 2025). "A study on medulloblastoma found that Foxp4 and Ezh2 are both targets of the microRNA miR-101-3p, indicating the function of these genes might be linked in some scenarios." (PMID 38419656, 2024). "MiR-101 could promote cell apoptosis in medulloblastoma targeting forkhead box P4 (FOXP4) and EZH2." (PMID 36497343, 2022).
ovarian carcinoma (4 papers, 2021 to 2025). A malignant neoplasm originating from the surface ovarian epithelium. "Deciphering the molecular mechanisms underlying FOXP4’s function holds promise for identifying novel therapeutic targets against cancer, thus necessitating a thorough exploration of FOXP4’s role and its correlation with ovarian cancer." (PMID 38740744, 2024). "The findings indicate FOXP4’s ability to activate the Wnt/β-catenin signaling pathway in ovarian cancer, which is vital for FOXP4’s oncogenic role." (PMID 38740744, 2024). "This study has pinpointed FOXP4 as a pivotal signaling factor impacting ovarian cancer (OV) tumor progression." (PMID 38740744, 2024). "Our findings reveal aberrant upregulation of FOXP4 mRNA, correlating with poor prognostic outcomes in ovarian cancer tissues, through integration of data from the TCGA and GEO databases." (PMID 38740744, 2024). "In this investigation, we delved into the intricate pathogenesis of ovarian cancer, shedding light on the pivotal role of FOXP4 as a potent oncogenic driver." (PMID 38740744, 2024). "From a mechanistic standpoint, the activation of the Wnt/β-catenin pathway augments FOXP4 transcription, thereby facilitating the proliferation and migration of ovarian cancer cells." (PMID 38740744, 2024). "In multiple single-cell sequencing datasets of ovarian cancer, we found that FOXP4 was predominantly expressed in malignant tumor cells, while it was expressed at lower levels in stromal cells and immune cells." (PMID 38740744, 2024). "The clinical significance of FOXP4 was assessed by examining the correlation between the FOXP4 transcript levels and the survival outcomes of ovarian cancer patients with the aid of the Kaplan-Meier Plotter tool." (PMID 38740744, 2024). "Moreover, ovarian cancer samples from the TCGA database were categorized into high and low FOXP4 expression groups for GSEA analysis." (PMID 38740744, 2024). "This series of changes revealed that β-catenin/FOXP4/PTK7 signaling pathway may affect the invasion ability of ovarian cancer cells by regulating EMT process." (PMID 38740744, 2024). "In conclusion, this investigation pioneers the recognition of FOXP4’s substantial upregulation in ovarian cancer and its direct correlation with adverse outcomes, underscoring the imperative for comprehensive insight into the molecular intricacies of ovarian cancer." (PMID 38740744, 2024). "Regulatory mechanisms involving the transcription factor FOXP4 have been shown to modulate PTK7, contributing to the malignant progression of ovarian cancer, though the specifics of downstream signaling regulation remain uncertain." (PMID 38740744, 2024). "Experimental evidence underscores FOXP4’s role as a transcriptional activator of PTK7, thereby facilitating ovarian cancer progression." (PMID 38740744, 2024). "This, in conjunction with PTK7’s activation of the β-catenin pathway, establishes a β-catenin/FOXP4/PTK7 positive feedback loop, culminating in the accelerated advancement of ovarian cancer." (PMID 38740744, 2024).
Autoimmunity (2 papers, 2023 to 2025). The occurrence of an immune reaction against the organism's own cells or tissues. "The combined loss of FOXP1 and FOXP4 in committed Treg cells results in increased cellularity of activated T cells, inflammatory cytokine secretion, GC B cell responses, and pathogenic antibody production resulting in systemic inflammation, autoimmunity, lymphoproliferation, and decreased lifespan." (PMID 40794436, 2025). "Our findings show that mice with combined, but not individual, deficiency in FOXP1 and FOXP4 exhibit lymphoproliferation, inflammation, autoimmunity, and early lethality." (PMID 40794436, 2025).
breast tumor (2 papers, 2016 to 2025). "rs1983891 is located in FOXP4, which belongs to subfamily P of the forkhead box (FOX) transcription factor family, and is associated with kidney tumors, larynx carcinoma, and breast tumors." (PMID 26828504, 2016). "Interestingly, FOXP4 is expressed highly in breast tumor tissues compared to adjacent normal tissues, and its upregulation is associated positively with many clinicopathologic factors, such as tumor size, pathological grade, and metastasis." (PMID 40231553, 2025).
cervical cancer (2 papers, 2021 to 2022). A primary or metastatic malignant neoplasm involving the cervix. "During cervical cancer development and progression, lncRNA FOXP4-AS1expression is upregulated, and it acts as a mir-136-5p ceRNA to regulate expression of polycomb protein 4 gene (CBX4) and accelerate the development of cervical cancer." (PMID 35577352, 2022).
congenital diaphragmatic hernia (2 papers, 2021 to 2022). A posterolateral defect of the diaphragm that allows passage of abdominal viscera into the thorax, leading to respiratory insufficiency and persistent pulmonary hypertension with high mortality. "Based on our findings we conclude that heterozygous FOXP4 variants can cause a neurodevelopmental disorder, with prominent speech/language problems, short stature, macrocephaly, overlapping dysmorphisms, congenital diaphragmatic hernia, and cervical vertebral abnormalities." (PMID 33110267, 2021).
endometrial cancer (2 papers, 2015 to 2024). Primary or metastatic malignant neoplasm involving the endometrium (mucous membrane that lines the endometrial cavity). "Using a FOXP4-overexpressed murine endometrial carcinoma-derived cell line, tumor formation was significantly promoted when they were subcutaneously transplanted into recipient mice of the same inbred strain with normal immune functions." (PMID 38890503, 2024). "To determine whether FOXP4 is a downstream target molecule of the androgen/AR pathway in endometrial cancer, we performed a Chip-sequence assay and found that androgen/AR or its transcription complex bound to intron 1 of the hFOXP4 coding region of AR_HEC50B cells." (PMID 38890503, 2024).
liver cancer (2 papers, 2022 to 2024). An epithelial or non-epithelial malignant neoplasm that arises from the liver. "Specifically, the virus-induced modification of Foxp4 through m6A regulation may play a role in the development of liver cancer linked to HBV infection." (PMID 39513116, 2024).
lung adenocarcinoma (2 papers, 2016 to 2023). A carcinoma that arises from the lung and is characterized by the presence of malignant glandular epithelial cells. "In addition, two additional loci, HLA class II at 6p21.32 (rs2179920; P =5.1 × 10−17, per-allele OR=1.36) and 6p21.1 (FOXP4) (rs2495239; P=3.9 × 10−9, per-allele OR=1.19) were newly identified as loci associated with EGFR mutation-positive lung adenocarcinoma." (PMID 27501781, 2016).
lung diseases (2 papers, 2022 to 2025). "FOXP4 is expressed in the proximal and distal airway epithelium and variants within this region have been linked to lung diseases." (PMID 35360730, 2022).
viral infection (2 papers, 2024). "The inhibition of Foxp4 by HBV may serve as one of the mechanisms that accelerates tumor development in cases of chronic virus infection." (PMID 39513116, 2024). "Furthermore, FOXP4 was also expressed in CD4 + and CD8 + T cells and necessary for memory T-cell cytokines recall responses to viral infection." (PMID 38429664, 2024).
autoimmune hemolytic anemia (1 paper, 2025). Autoimmune hemolytic anemia (AIHA) is an autoimmune disorder in which various types of auto-antibodies are directed against red blood cells causing their survival to be shortened and resulting in hemolytic anemia. "cDKO mice also had detectable serum anti–red blood cell (RBC) antibodies, whereas no RBC-specific antibodies were detected in >500-day-old CrePos mice, suggesting FOXP1- and FOXP4-deficient Tregs develop lethal autoimmune hemolytic anemia (AIHA)." (PMID 40794436, 2025).
cervical intraepithelial neoplasia (1 paper, 2024). "Recently, we reported that forkhead box transcription factor P4 (FOXP4) is associated with the androgen/AR pathway in cervical intraepithelial neoplasia cells." (PMID 38890503, 2024).
ciliary body disorder (1 paper, 2025). A disease involving the ciliary body. "Our cohort studies suggest that similar FOXP4 variants are likely to be a rare cause of plateau iris and ACG overall, although it is interesting that FOXP4 has a nominally significant association with iris/ciliary body disorders in Genebass." (PMID 40637512, 2025).
developmental delays (1 paper, 2021). "It is thus not surprising that we found a broad range of associated phenotypes in individuals with likely pathogenic FOXP4 variants, including growth deficits, developmental delays and a spectrum of associated congenital abnormalities." (PMID 33110267, 2021). "In conclusion, through clinical characterization and functional assays, we implicate heterozygous FOXP4 variants in a neurodevelopmental disorder with mild developmental delays, most prominently in the speech/language domain." (PMID 33110267, 2021).
encephalitis (1 paper, 2016). An acute inflammatory process affecting the brain parenchyma. "Although the role of CD4+Foxp4+ Tregs in flavivirus encephalitis remains elusive, CCR5-dependent recruitment of CD4+Foxp3+ Tregs may play certain roles in the control of encephalitis progression caused by flavivirus infection." (PMID 27439902, 2016).
endometrioid carcinoma (1 paper, 2024). "FOXP4 was expressed in the spontaneously developed endometrioid carcinoma of Ptenff/PRcre/+ mice, and its expression was decreased by DHT treatment." (PMID 38890503, 2024). "This study indicates that the androgen/AR system suppresses the malignant activity of endometrioid carcinoma through the downregulation of FOXP4 which will impact new developments in clinical approaches to elderly health." (PMID 38890503, 2024). "Furthermore, clinical data concerning the expression profiles of FOXP4 and AR in endometrioid carcinoma support our experimental conclusion that the progression of endometrioid carcinoma can be controlled by stimulating an androgen/AR system and/or suppressing its downstream molecular target, FOXP4." (PMID 38890503, 2024). "In addition, when a murine endometrioid carcinoma-derived cell line, PPP268, was transfected with FOXP4 and subcutaneously allografted in C57BL/6 N mice, tumor formation was significantly promoted as compared with wild-type PPP268." (PMID 38890503, 2024).
glaucoma (1 paper, 2025). Increased pressure in the eyeball due to obstruction of the outflow of aqueous humor. "We also reviewed more than 20,000 patients (primarily from the UK Biobank) diagnosed with glaucoma and/or disorders of the iris and ciliary body for additional FOXP4 variants and functionally validated them as described." (PMID 40637512, 2025). "We then did the same for all Genebass glaucoma patients because FOXP4 is a known GWAS locus for OAG." (PMID 40637512, 2025). "The other potential candidate was missense substitution c.1433 A>G (p.Q478R) in Forkhead Box P4 (FOXP4, ENST00000307972), which belongs to a family of transcription factors implicated in multiple forms of ASD and glaucoma." (PMID 40637512, 2025). "We did not see a similar relationship between FOXP4 variants and glaucoma despite prior GWAS data supporting a clear association." (PMID 40637512, 2025). "The broad developmental expression of FOXP4 and its role in anterior segment disease also warrant further studies exploring the links between other FOXP transcription factors, such as dimerization partners FOXP1 and FOXP2, in glaucoma and ASD." (PMID 40637512, 2025).
hyperopia (1 paper, 2025). A refractive error in which rays of light entering the eye parallel to the optic axis are brought to a focus behind the retina, as a result of the eyeball being too short from front to back. "To determine the prevalence of FOXP4 mutations in cases of ACG, we first screened an in-house cohort of 37 patients diagnosed with plateau iris, ACG, and/or high hyperopia." (PMID 40637512, 2025).
language disorder (1 paper, 2025). A category of disorders characterized by an impairment in the development of an individual's language capabilities, which is in contrast to his/her non-verbal intellect. "Further, the FOXP4 SNPs are associated with neurodevelopmental disease, sensorineural hearing loss, speech/language disorder, and brain development." (PMID 40724930, 2025).
laryngeal squamous cell carcinoma (1 paper, 2022). A squamous cell carcinoma that arises from the larynx. "FOXP4 directly acts on LEF-1 and gives impetus to the occurrence of laryngeal squamous cell carcinoma." (PMID 36160018, 2022).
Obesity (1 paper, 2024). Accumulation of substantial excess body fat. "In this study, we explored a gene therapy approach to treat obesity in agouti mice using adeno-associated viruses (AAVs) carrying PRDM16, FoxP4, or Follistatin (FST) genes, which are known to promote the browning of white adipose tissue." (PMID 39596212, 2024).
oral squamous cell carcinoma (1 paper, 2021). "miR-299-3p was found to inhibit oral squamous cell carcinoma cell proliferation by targeting forkhead box P4 (FOXP4) expression thereby promoting apoptosis." (PMID 33806361, 2021).
pulmonary fibrosis (1 paper, 2024). Chronic progressive interstitial lung disorder characterized by the replacement of the lung tissue by connective tissue, leading to progressive dyspnea, respiratory failure, or right heart failure. "A recent study on pulmonary fibrosis has revealed that the alterations in miR-423-5p and its target gene forkhead box p4 (FOXP4) have a significant impact on the expression of the PI3K/AKT/mTOR pathway." (PMID 39479511, 2024).
Splenomegaly (1 paper, 2025). Abnormal increased size of the spleen. "Treg-specific deletion of both FOXP1 and FOXP4 in cDKO mice resulted in splenomegaly and peripheral lymph node (pLN) enlargement." (PMID 40794436, 2025).
thyroid cancer (1 paper, 2022). "Lower FOXP1, FOXP2 and higher FOXP3, FOXP4 levels could be identified in thyroid cancer tissues when compared with matched normal tissue." (PMID 36203616, 2022).
toxoplasmosis (1 paper, 2012). A parasitic disease contracted by the ingestion or fetal transmission of toxoplasma gondii. "Given that effector function of Foxp4 cKO splenocytes showed a trend toward decreased response to STAg stimulation, we also asked whether the functionality of T cells in the brain, a site at which constant antigen presentation occurs during toxoplasmosis, was altered." (PMID 22912696, 2012).
tumor (27 papers, 2015 to 2026). "They found that miR-101-3p and miR-423-5p function as tumor suppressors through the direct regulation of a common gene, FOXP4, which is responsible for encoding a transcription factor that plays a crucial role in embryonic development and tumorigenesis." (PMID 38730633, 2024). "We also identified Foxp4 as a candidate transcription factor underlying gene expression differences in NT and Bcl9-KD tumor cells." (PMID 34026600, 2021). "These exosomal miRNAs act as tumor suppressors by inhibiting growth, migration, and invasion of tumor cells, as well as elevating apoptosis via targeting the FOXP4 transcription factor and EZH2 histone methyl transferase." (PMID 39805813, 2025). "In OC, members such as FOXA1, FOXM1, FOXP4, FOXQ1, and FOXR2 primarily exhibit oncogenic functions, whereas others like FOXO and FOXP1 are associated with tumor-suppressive effects." (PMID 40746724, 2025). "Next, we expanded our investigation of FOXP4’s biological function to include tumor cells’ capacity for migration and invasion." (PMID 38740744, 2024). "Suppression of FOXP4 markedly attenuates tumor cell proliferation and inhibits tumor growth, with implications potentially linked to the EMT pathway." (PMID 38740744, 2024). "In mouse xenograft tumor models, FOXP4 knockdown diminished tumor growth, yet reintroducing PTK7 partially reversed this effect." (PMID 38740744, 2024). "Tumor formation was also promoted when FOXP4(+) HEC59 cells were subcutaneously transplanted into nude mice." (PMID 38890503, 2024). "Tumor formation was also inhibited when FOXP4-downregulated HEC50B cells were subcutaneously transplanted into nude mice." (PMID 38890503, 2024). "Considering the Wnt/β-catenin signaling pathway’s pivotal role in tumor cell function, we delved deeper into FOXP4’s potential to influence this pathway’s activity." (PMID 38740744, 2024). "Taken together, these results suggest that PTK7 plays a critical role in facilitating FOXP4’s tumor-promoting effects in OV cells, highlighting the importance of PTK7 suppression in this context." (PMID 38740744, 2024). "TISIBD was employed to analyze the relationship between FOXP1, FOXP2, FOXP3, and FOXP4 and tumor-infiltrating immune cells in 28 kinds of tumor." (PMID 36203616, 2022). "We confirmed global epigenetic modification associated with reduced H4R3me2S and re-expression of tumour suppressors, such as EIF3F, FOXP4, ZBTB4, GANAB, TMEM141, in association with loss of clonogenicity." (PMID 33795785, 2021). "FOXP1 and FOXP2 fall under the FOXP sub-family (also comprising FOXP3 and FOXP4) which has functions in oncogenic and tumor suppressive pathways." (PMID 32066696, 2020). "CircABCC4 mechanically sponges miR‐1182 expression to promote FOXP4 expression and, consequently, accelerates tumor progression." (PMID 31270953, 2019). "This is one explanation as to why miR-491-5p is downregulated in OS—because it acts as a tumour suppressor via knockdown of FOXP4." (PMID 28272374, 2017). "To investigate whether PTK7 mediates the tumor-promoting function of FOXP4 in OV, we generated FOXP4 knockout cells with stable expression of exogenous PTK7." (PMID 38740744, 2024). "Tumor size and weight were significantly reduced after FOXP4 silencing compared with the control." (PMID 38740744, 2024). "Together, these results indicate that the involvement of FOXP4 in OV tumor development promotion." (PMID 38740744, 2024). "Moreover, they demonstrated that hsa-miR-3180-3p inhibited proliferation and metastasis of NSCLC by downregulating FOXP4, a transcription factor that promotes tumor growth and invasion." (PMID 37894277, 2023). "Furthermore, FOXP4 drives the mRNA expression of proteins pertinent to the Wnt/β-catenin signaling pathway, a pathway widely acknowledged for its pivotal regulatory role in tumor cell proliferation, migration, and invasion." (PMID 38740744, 2024).